CD80 (CD80 molecule)
Diseases named in the same sentence as CD80 in open-access papers (continued):
Sharing a sentence is not in itself a finding about the gene and the disease.
tumor (continued). "Moreover, TREM2 inhibited macrophage-expressed antigen-presenting molecules MHC-I/II and the coactivators CD80/CD86, suggesting that TREM2 also affects T cell-mediated anti-tumor immune response." (PMID 39135069, 2024). "In addition, we sought to visualize epithelial cells, M1 and M2 macrophages in the tumor microenvironment with PAN‐CK, CD80, and CD163 specific antibodies as the biomarkers." (PMID 35789544, 2023). "Furthermore, the combination of OX40L with CD80 or CD86, or OX40L with IL-12 dramatically increased both survival and tumor growth delay." (PMID 36839944, 2023). "Indeed, it has been shown that dendritic cells (DCs) that engulf tumor cells treated with recombinant TcCalr mature —represented by an increased expression of MHC II class molecules, CD80, and CD86, among other markers— in a dual canine tumor model." (PMID 36993959, 2023). "Additionally, the analysis of the CGGA and TCGA databases also showed that CDCA7 was closely related to several tumor-related suppressors, including CD80, CD276, CD28, PDCD1LG2, and TNFSF4, which contribute to tumor development via multiple mechanisms." (PMID 37510310, 2023). "However, our data demonstrating decreased MHC-I, MHC-II, CD80, and CD86 expression as A20 tumors progress provide additional context to the mechanism of this enhanced anti-tumor response." (PMID 37016127, 2023). "For example, studies have demonstrated that tumor-infiltrating DCs exhibit decreased expression of co-stimulatory molecules such as CD86 and CD80, while concurrently displaying heightened expression of immune inhibitory molecules such as programmed cell death 1 ligand 1 (PD-L1)." (PMID 38012715, 2023). "In addition, IL-6 limits anti-tumor T-cell responses by promoting the differentiation of M2 macrophages or acting on dendritic cells to inhibit the expression of MHC-II, CD80/86, and IL-12 and promote IL-10 production." (PMID 38026978, 2023). "Both classical (CD103−) and cDC1s (CD103+) with increased expression of the co-stimulatory molecules CD80 and CD40, essential for priming tumor-specific CTLs,18 were observed in increased numbers in OrfV-treated mice shortly thereafter the peak of the NK response." (PMID 38075247, 2023). "To test gene induction, we co-transfected them transiently with crRNAs and trans-activating CRISPR RNA (tracrRNA) to induce the transcription of genes commonly expressed by tumor cells (e.g. CD274, NT5E) or genes not expressed by tumor cells such as CD80." (PMID 37732732, 2023). "CD80 overexpression amplifies immunogenicity because it increases same cell (cis) CD80:PD-L1 interactions, which (i) disrupt binding of T-cells PD-1 inhibitory receptors with their ligands (PD-L1) in tumour cells, and (ii) inhibit CTLA-4 inhibitory receptors binding to CD80 in tumour cells." (PMID 37468749, 2023). "The functional significance of the CD80:PD‐L1 interaction is seen in vivo whereby CD80 or PD‐L1 mutants lacking the ability to interact show attenuated immune responses due to excess engagement of PD‐1, thereby limiting tumour immunity." (PMID 36727298, 2023). "Furthermore, increased DC expression of costimulatory CD80/CD86 was observed in the TME, consistent with the substantial increase in the tumor CD8+ T cells in SAProsome-3–treated mice." (PMID 37524727, 2023). "CTLA-4 is another popular inhibitory immune checkpoint that could competitively bind CD80 and CD86 against CD28, interrupting the activation of anti-tumor immunity." (PMID 37305457, 2023). "Consistently, moDCs phagocytosed more DOX@3D-MPs-treated tumor cells compared with PBS-treated group, leading to their efficient maturation as indicated by the elevated percentages of costimulatory molecules CD80+ and CD86+ cells in moDCs." (PMID 37875473, 2023).
tumor (continued). "LID + US also significantly increased the percentage of CD80 + DC in the tumor, increased the percentage of CD86 + DC in the tumor-draining lymph nodes, and enhanced the phosphorylation of TBK1 and IRF3, which were related to the activation of STING pathway in the tumor tissue." (PMID 37391428, 2023). "The relatively low overexpression of PD-L1 and CTLA-4 on the surface of 4T1 cells after PDT, and the high overexpression of CD80, raised the expectation that PDT-ICB combinations could improve the treatment outcome in this tumour model." (PMID 37468749, 2023). "They all have their own ligand on APC (such as CD80, CD86 for CTLA-4 or PD-L1 and PD-L2 for PD-1), and tumor cells, depending on tumor types, may substitute them, thus using this immune checkpoint machinery to avoid cell killing." (PMID 37370768, 2023). "In tumor-immune interactions, the antitumor outcome is guided by various paired stimulatory and inhibitory receptor families (including PD: PD-L1, CD155: TIGIT, CD80: CTLA4, etc.)." (PMID 37838774, 2023). "Multivariate COX analysis confirmed that reduced CD80 expression was an important independent risk factor for the development of LUAD and was associated with age and sex, but not with tumor stage." (PMID 36892747, 2023). "Full activation of T cells requires that the main signal is recognized by the T‐cell receptor and antigen peptide/major histocompatibility complex, and the auxiliary signals driven by co‐stimulatory molecules, such as CD80 and CD86, which are present on tumor or antigen‐presenting cells (APCs)." (PMID 37476068, 2023). "Furthermore, myeloid cells possibly suppress anti-tumor responses by secretion of IL10 and interaction via CD80/CD86 with CTLA-4 on reactive CD8+ T cells." (PMID 36761972, 2023). "PD-L1 is a transmembrane protein that suppresses immune responses by binding to two inhibitory receptors, PD-1 and B7-1 (CD80), and it is strongly expressed on the surface of tumor and non-transformed cells in the tumor microenvironment." (PMID 37892225, 2023). "Furthermore, MC38‐tumor‐infiltrating cDC1 also showed upregulated CD40, CD80, CD86, and MHC‐II expression after RA and anti‐PD‐1 combination treatment." (PMID 36876644, 2023). "Finally, to investigate a potential transactivation of CAR T cells by tumor cells, we checked the expression of co-stimulatory ligands, such as CD70, 41BBL, CD80, and CD86, on BxPC-3 tumor cells by flow cytometry." (PMID 37287982, 2023). "MiR-4669-enriched exosomes suppressed CD80 and TNF-α in RAW264.7 cells, suggesting a direct impact of exosomal miR-4669 on the suppression of M1 macrophage activity to generate an immunosuppressive tumor microenvironment." (PMID 37175615, 2023). "They utilized a charge-altering releasable transporter mRNA delivery platform to induce the local expression of cytokines (CD70, IL-12, and IFN-γ) and costimulators (OX40L, CD80, and CD86) individually and in combination in two tumor models (A20B-cell lymphoma and CT26 colon carcinoma)." (PMID 36839944, 2023). "Furthermore, we obtained four genes (GIMAP6, CD80, IL16, and CCR2) that had predictive advantages for tumor purity using random forest classification and random forest regression." (PMID 35280857, 2022). "In summary, our results suggest that CD80 and PD1 might play a synergistic role in regulating immune and inflammatory responses to promote tumor progression." (PMID 35814211, 2022). "Further, CT26 tumor cells bind CTLA-4Ig, but much more faintly with a similar CD28Ig chimeric protein, thus providing an explanation for the dominant inhibitory effects on tumor immunity displayed by CD80." (PMID 35572581, 2022). "The free drug and SPIND2 injection did not obviously increase the population of matured DCs (CD80+CD86+) in tumor-draining lymph nodes (TDLNs) compared to the saline control group." (PMID 35821238, 2022).
tumor (continued). "Preclinical studies using murine tumor models have indicated an increase in the number of activated dendritic cells (APCs) as evidenced by increased expression of MHC class II, CD80, and CD86, as well as increased levels of IL-12 and IFNγ in the tumor microenvironment post HIFU." (PMID 35848421, 2022). "The combination of cisplatin and 5-fluorouracil also induced a significant release of HMGB1, DC maturation/activation, upregulation of CD80 and CD86 in tumor cell ICD response, and further enhancement of the host antitumor immune response with a favorable prognosis." (PMID 36466838, 2022). "While CD80 has been considered to be a leading costimulator for T cells through CD28, to our surprise, CD80 costimulation did not improve tumor control." (PMID 36073543, 2022). "We observed a non-significant difference in tumor expression of PD-L2 and tumor-infiltrating dendritic cell (CD80) proteins between the 5 groups." (PMID 36483592, 2022). "For optimal T-cell–mediated anti-tumor immunity, T cells must recognize an antigen presented on major histocompatibility complexes (MHC) through the T-cell receptor (TCR) and receive a co-stimulatory signal through CD28 engagement with CD80/CD86." (PMID 36248881, 2022). "All the treatments including OVA resulted in expressions of CD40 and CD80 but not CD86 in tumor-derived macrophages." (PMID 36551577, 2022). "Thus, by removing sialic acid ligands on the surface of tumor cells, CD28 is better able to engage CD80, accounting for increased co-stimulation of T cells." (PMID 36316782, 2022). "Differing from studies that relied on engineered tumor cell lines with gene overexpression in B cells or APCs, our model exclusively used primary LECs, which do not express CD80 or PD-1, to show a trans interaction of CD80/PD-L1." (PMID 35449134, 2022). "In addition, cytotoxicity enhanced the expression of the T-cell costimulatory ligands CD70, CD80, and CD86 while stimulating tumor infiltration of APCs, thus improving the antitumor effects." (PMID 36185263, 2022). "We propose that these cells might have a role in antigen presentation and activation of T lymphocytes in the tumour microenvironment, because of expressed MHCII, CD86 and CD80 markers." (PMID 36551739, 2022). "We sought to apply iFRET to directly quantify PD-1/PD-L1 and CTLA-4/CD80 interactions in a cohort of patients in both their pre- and post-RFA-treated lung metastases, and iFRET results were correlated with the quantification of tumor-infiltrating lymphocytes." (PMID 36497220, 2022). "The infiltration of CD80+ cells was not significantly different in tumor, paratumor, and normal tissues of patients with RCC and LCC." (PMID 35936748, 2022). "Interestingly, we observed that treatment with oxaliplatin (3.0 mg/kg, i.v.)significantly increased the populations of CD86+CD80+ and CD8+CD45+ cells in the tumor tissues as compared to the control and cisplatin-treated groups." (PMID 36131787, 2022). "We cocultured PDAC tumor cells with FMS‐like tyrosine kinase 3 ligand (Flt3L‐induced DCs, consisting of a mixture of cDC1 and cDC2 cells, and then the expression of costimulatory molecules CD80 and CD86 on DCs were examined." (PMID 35064757, 2022). "Furthermore, we found that CSF-1R was significantly correlated with tumor-related immunosuppressive molecules (including PDCD1, CTLA4, CD80, CD86, HAVCR2)." (PMID 35444953, 2022). "Similarly, RH-Δcps have been reported to invade mature macrophages and DCs, increase the expression of CD80 and CD86, and reprogram the suppressed myeloid cells to alleviate tumor immunosuppression." (PMID 36118042, 2022). "The [CD80/OVA]NPs showed significant inhibitory effect in the treatment of either prophylactic B16 or therapeutic B16 tumor model and significantly improved the survival rate of tumor‐bearing mice." (PMID 37324583, 2022).
tumor (continued). "Moreover, this biocomplex regulated the secretion of tumor-related cytokines (i.e., GM-CSF, TNF, and IL-6) and promoted the activation of immune cell surface markers (i.e., CD80+, CD86+, and CD40+)." (PMID 36059807, 2022). "All armed OVs, including OV-OX40L, OV-IL12, and OV-OX40L/IL12, increased the expression of the costimulatory receptors CD80 and CD86 on tumor cells, with the strongest upregulation observed in cells infected with OV-OX40L/IL12, followed by OV-OX40L and OV-IL12." (PMID 35715953, 2022). "We divided the 443 TCGA LUAD samples with complete clinical data into high and low groups according to tumor purity, and obtained CSGTPP (0.21*CCR2+ 0.06*GIMAP6+0.64*CD80+ 0.21*IL16) with LASSO regression analysis, and then divided the samples into high and low two groups." (PMID 35280857, 2022). "Next, we evaluated the populations of CD86+CD80+ and CD8+CD45+ cells in the tumor tissues." (PMID 36131787, 2022). "Whether CTLA4 also depletes Teff CD80, and whether Teff CD80 and Treg CTLA4 regulate Teff reinvigoration or migration, and hence tumor regression, need further investigation." (PMID 35449134, 2022). "Tumor cells are also able to escape from NK lysis due to their lack of expression of costimulatory molecules, such as B7-1 (also known as CD80), B7-2 (or CD86), CD40 and CD70, that hinder the optimal activation of these cells." (PMID 35335881, 2022). "Due to that CD80/CD86-CTLA4 axis were involved in the crosstalk between myeloid cells and T cells, and that the application of CTLA4 blockade has been widespread in tumor immunotherapy, we investigated the value of targeting CD80/CD86-CTLA4 axis under inflammatory conditions." (PMID 36443332, 2022). "Only the expression of CD80 tended to be higher, when DCs co-cultured with tumor cells are compared to the DCs without the maturation cocktail." (PMID 35565180, 2022). "However, co-culture of the ORFV NA1/11-infected tumor cells with DCs significantly enhanced CD80 and CD86 expression on DCs, consistent with the notion that ORFV NA1/11-infected tumor cells enhanced the activation of surround DCs." (PMID 35959371, 2022). "RT significantly enhanced the abundance of tumor-infiltrating CD317+CD11c+ pDCs and the injection of PIC into the radiated tumors increased the percentage of CD80+ cells, one of the markers of TLR-9 activation, among pDCs, when compared to the untreated control group 36,43." (PMID 35999216, 2022). "In addition to upregulation of CTLA-4 and PD-1 on tumor-infiltrated T cells, in many tumors, the CD28 ligands CD80 and CD86 are poorly expressed both on tumor cells and tumor-associated myeloid cells." (PMID 35379805, 2022). "These tolerogenic DCs present tumor antigen without proper costimulation (CD80/CD86), express inhibitory molecules (PDL1/CTLA4), and secrete immunosuppressive factors (TGF-β, IL-10, IL-27, NO, Arg, and IDO)." (PMID 35972798, 2022). "In contrast, the percentage of CD80+ or PD-L1+ monocytes/macrophages and neutrophils did not change within the tumor." (PMID 36059473, 2022). "M1 macrophages usually expressed MHC-II, CD68, CD80, and CD86 and had the effect of antitumor and pro-inflammation, while the M2 microphage in the tumor microenvironment could play a role in pro-tumor, immunosuppression, and anti-inflammation." (PMID 35004850, 2021). "The IPLD-treated mice had as high as 53.6% CD80+CD86+ mDCs in TDLNs compared with 24.6% in the PLD-treated mice and 11.0% in the PBS group, promoting the recruitment of T cells into the tumours." (PMID 33893275, 2021). "Given their expression of PVR, TNFRSF14 and CD80/CD86, they might be under direct control by TIGIT+CTLA4+CSF2+TNFSF14+ tumor cells." (PMID 33968070, 2021). "The binding of CTLA4 to its ligands CD80 and CD86 leads to tumor cell immunosuppression." (PMID 34143198, 2021). "The impact of CD80 expression on tumor cells on the efficacy of CTLA-4 blockade has not been sufficiently investigated yet." (PMID 33923750, 2021).
tumor (continued). "TAMs with M1 profile usually expressed MHC-II, CD68, CD80, and CD86 and had important antitumor and pro-inflammation function, while the M2 microphage in the tumor microenvironment could play a role in pro-tumor and anti-inflammation." (PMID 34122523, 2021). "We, therefore, assume that PD-L1 on tumor cells did not effectively control the CTLA-4/CD80 axis in TC-1- and TC-1/dCD80-1-induced tumors." (PMID 33923750, 2021). "Genes upregulated in both tumor and TAS of BA PCa patients as compared to WA included cell cycle markers CD19, CD2, CD53 and CD80, interferon response factor 8 (IRF8), phosphoinositide 3-kinase (PIK3CA), mechanistic target of rapamycin (mTOR), and metastasis-associated protein S100A4." (PMID 34316327, 2021). "Moreover, the authors showed that RES effectively stimulated the infiltration of high level of DCs (CD80+/CD86+) and cytotoxic CD8+ T-cells into tumor tissue of xenograft tumor model established with ID8 cells." (PMID 33440842, 2021). "The colonic APCs’ superior protein uptake and subsequent upregulation of CD80 and PD-L1 compared to tumor APCs, plus the enhanced IFN-γ responses of colonic T cells might indicate different functional propensity fostered in tumor vs. colon." (PMID 34680397, 2021). "T cell activation occurs when an APC presents tumor Ag via major histocompatibility complex (MHC) to the TCR, leading to interaction between costimulatory receptor CD28 on the T cell and B7 (specifically CD80 and CD86) on an APC." (PMID 34201529, 2021). "Importantly, POLD1 expression was associated with immune checkpoint molecules, including CD274, CD80, CD86, CTLA4, PDCD1 and TCGIT, and facilitated an immune-excluded tumor microenvironment." (PMID 34868924, 2021). "There was also similar expression of Cd80, Cd86, Fcgr1, Fcgr3 and Fcgr4 in the tumor tissues (data not shown)." (PMID 34774008, 2021). "Even in the absence of tumour cell apoptosis, cGAMP treatment-induced DC maturation, manifested by 4-, 6-, and 2-fold increases of CD80, CD86, and MHC-II, respectively, compared to PBS treatment." (PMID 34285232, 2021). "To this end, we developed a novel chimeric receptor that can recognize CD80 and CD86 as tumor antigens on malignant B cells by combining the extracellular and transmembrane domains of CTLA4 with the intracellular signaling domains of CD28 and CD3z and explored its potential in cancer treatment." (PMID 33868277, 2021). "Our tumour compartment specific multivariate signature for response was largely consistent with the DE results, comprising higher levels of fibronectin, GZMA and STING and lower EPCAM and CD80 (AUC = 0.875)." (PMID 35083152, 2021). "It has been suggested that TAMs with an M2-like phenotype (markers CD163, CD204, and CD206) have a pro-tumor effect while M1-like TAMs (CD68, CD80, and CD86) may have an anti-tumor effect." (PMID 33882057, 2021). "For example, cancer cells and tumor-antigen presenting cells are shown to express high levels of coinhibitory receptor ligands (PD-L1, PD-L2 and many other) with relatively low levels of costimulatory receptor ligands (CD80 and CD86) in the tumor microenvironment to promote T cell anergy." (PMID 33717081, 2021). "Interestingly, tumor-induced Bregs express high levels of CD80 and CD86, suggesting that CD80 and CD86-mediated contacts between Bregs and their target cells are essential for suppressing T cell response and Bregs-induced Tregs differentiation." (PMID 33767709, 2021). "Overall, induced T cell activation in cell suspensions from colon or tumor did not result in distinct patterns of CD80 and PD-L1 expression on co-residing APCs." (PMID 34680397, 2021). "At each depth, expression levels of representative biomarkers of cellular apoptosis (caspase-3, termed as Cas-3), ICD (high mobility group box 1 protein, termed as HMGB1), and DC maturation (CD80 and CD86) were examined by immunofluorescent staining of tumor sections." (PMID 33531498, 2021).